INS (insulin)
Diseases named in the same sentence as INS in open-access papers (continued):
Sharing a sentence is not in itself a finding about the gene and the disease.
diabetes (continued). "SPI1 and MTF1 were two novel upstream ΤFs identified which have been suggested to be involved in the inflammatory cascade and insulin regulation in diabetes." (PMID 39974596, 2025). "This individual was elderly, lost weight, and had a 7% spike in her HbA1c, which required the addition of insulin to her diabetes regimen; her ENDPAC score was 11, which is the maximum (high-risk ≥5)." (PMID 40439123, 2025). "Diabetes mellitus, characterized by chronic hyperglycemia, arises from insufficient insulin production, impaired insulin action, or a combination of both." (PMID 40485856, 2025). "Type 1 diabetes mellitus (T1DM), also referred to as autoimmune diabetes, is a persistent condition marked by a deficiency of insulin due to the loss of pancreatic β‐cells, resulting in hyperglycemia." (PMID 40765373, 2025). "For instance, while insulin therapy is critical for managing diabetes, it can occasionally lead to a condition known as hypoglycemic encephalopathy." (PMID 40491970, 2025). "Patients with diabetes often develop hyperinsulinemia, and studies have indicated that higher estrogen in females can enhance the sensitivity of peripheral tissues to insulin, thereby partially counteracting the pro-carcinogenic effects of hyperinsulinemia." (PMID 40933886, 2025). "A key element of structured treatment and teaching programmes is to prepare people with diabetes and insulin therapy to prevent hypoglycaemia or to react appropriately if symptoms of hypoglycaemia occur." (PMID 40818105, 2025). "Significant global disparity and an association between glycemic outcomes and the accessibility of diabetes technologies and insulin were found." (PMID 40864470, 2025). "Studies have shown that DNAm alterations occur in the pancreatic islets, liver, and skeletal muscle of individuals with diabetes, which disrupt gene expression and impair insulin secretion, ultimately leading to metabolic dysregulation." (PMID 40380284, 2025). "CGM accuracy decreased from people with diabetes receiving subcutaneous insulin therapy (MARD: 13.9%; %20/20: 81.5%) to those with ITT (MARD: 50.8%; p < 0.01, %20/20: 67.5%; p .02)." (PMID 41448958, 2025). "This is a particularly important property of quercetin, given the critical role of skeletal muscle in the pathogenesis of diabetes, as well as insulin resistance." (PMID 40806520, 2025). "This sustained inflammasome activity can contribute to β-cell damage, impairing glucose sensing and insulin secretion, and thereby accelerating diabetes pathogenesis." (PMID 40136648, 2025). "Diabetes mellitus is a metabolic disorder characterized by chronic hyperglycaemia, occurring due to defects in insulin secretion, insulin action, or both." (PMID 41007688, 2025). "We observed that patients who controlled diabetes with healthy eating had a slightly higher level of QoL than those who relied on insulin." (PMID 40837917, 2025). "The goal of the drugs currently used to treat diabetes is to enhance the amount of insulin released by pancreatic cells, improve the insulin sensitivity of insulin target tissues, or both." (PMID 39796627, 2025). "As for the analysis of adiposity measures, diabetes exhibited a strong correlation with glucose and insulin measures among participants." (PMID 40937951, 2025). "The PI3K/AKT/mTOR, NF-κB, and MAPK signaling pathways, along with oxidative stress, play crucial roles in diabetes and its complications by regulating glucose metabolism and insulin sensitivity." (PMID 40871631, 2025). "Type 2 diabetes mellitus (T2DM) is a metabolic disorder caused by impaired insulin secretion and impaired tissue sensitivity to secreted insulin, resulting in chronic hyperglycemia." (PMID 39630234, 2025). "In the study of impaired glucose and lipid metabolism, FoxO signaling and insulin signaling shared a common pathological mechanism for AD and diabetes." (PMID 39891057, 2025).
diabetes (continued). "The company supports data synchronization from over 95% of global diabetes and health monitoring devices, including blood glucose meters, insulin pumps, CGMs, and fitness trackers." (PMID 39911718, 2025). "On the other hand, type 2 diabetes mellitus, which constitutes 90-95% of cases, is predominantly due to the gradual decline in insulin secretion capacity and is typically accompanied by insulin resistance." (PMID 40391013, 2025). "Most of the proteins found in our study are partly involved in the metabolisms of glucose and insulin, contributing to the etiology of diabetes." (PMID 39941463, 2025). "Our objective is to compare the real-world effectiveness and safety of insulin biosimilars versus reference products in adults with diabetes mellitus." (PMID 40737300, 2025). "Anti-diabetic nano-formulations represent a significant advancement in the field of diabetes treatment, capable of reducing enzymatic degradation of specific anti-diabetic drugs, such as insulin, within the gastrointestinal (GI) tract." (PMID 40448105, 2025). "Technologies such as continuous glucose monitoring (CGM) systems have revolutionized diabetes care, providing instant glucose readings to help patients adjust their insulin doses in real time." (PMID 40507811, 2025). "Appropriately combined aerobic and resistance exercises enhance insulin sensitivity and glucose metabolism, underscoring physical activity’s vital role in diabetes prevention and management." (PMID 41516982, 2025). "A second is in an in‐patient or emergency department care where a professional in another speciality finds someone with diabetes taking insulin under their care; often here it will be necessary to access the expertise of the hospital's diabetes team." (PMID 40035222, 2025). "HMNs have the ability to transform diabetes management by enabling continuous glucose monitoring and glucose-sensitive insulin delivery." (PMID 40136911, 2025). "The mean HbA1c level of children with type 1 diabetes was 9.4 ± 0.2, the mean duration of diabetes was 29.4 ± 4.4 months and the mean insulin dose was 0,94 ü/kg/day." (PMID 38879626, 2025). "Although insulin and many artificially synthesized oral hypoglycemic medications are available to treat diabetes, but insulin cannot be taken orally and the synthetic medicines now in use can cause substantial toxicity and side effects." (PMID 40828850, 2025). "The use of RBE resulted in a notable increase in PrkC levels in the diabetes-treated groups compared to insulin (p > 0.001)." (PMID 40536613, 2025). "Lack of PDX-1 due to the increased level of ROS ultimately inhibits insulin production and exacerbates diabetes." (PMID 40143138, 2025). "By stimulating eNOS, activating AMP-activated protein kinase (AMPK), and promoting GLUT4 translocation, Nebivolol enhances endothelial function, induces vasodilation, and improves insulin sensitivity in patients with diabetes or metabolic syndrome." (PMID 41463309, 2025). "Diabetes mellitus refers to a group of chronic metabolic disorders characterized by elevated blood glucose levels (hyperglycemia) resulting from defects in insulin secretion, insulin action, or both." (PMID 40298887, 2025). "From the SHAP-based ranking, the top six features based on mean SHAP values were: corresponding to Glucose, BMI, Age, Diabetes Pedigree Function, Pregnancies, and Insulin." (PMID 41153292, 2025). "Diabetes management was performed by regular staff, guided by diabetes teams using insulin titration algorithms based on either point-of-care glucose testing (POC arm) or continuous glucose monitoring (CGM arm)." (PMID 40980547, 2025). "Diabetes mellitus is a long-term metabolic condition marked by sustained high blood glucose levels, resulting from insulin resistance, insufficient insulin production, or a combination of both." (PMID 40278284, 2025). "Patients subsequently watched a video providing information about type 2 diabetes mellitus and insulin therapy." (PMID 41446519, 2025).
diabetes (continued). "Although the subjects in the Diabeloop group and especially those in the Control-IQ group were younger than those in Minimed 780G group, the 3 groups were similar with regard to BMI, age at onset and duration of diabetes, and daily insulin requirement." (PMID 39576311, 2025). "“Intermediate” care involves two to four blood glucose checks per day, multiple daily injections of insulin, availability of Hemoglobin A1C (HbA1c) testing and other complication screening, and access to diabetes education with social support." (PMID 41397006, 2025). "Participants had a duration of diabetes of at least 10 years and were well established on insulin treatment before admission." (PMID 41358572, 2025). "Insulin therapy, which is often needed for elderly patients with uncontrolled diabetes, can affect oral health." (PMID 40896019, 2025). "Particularly in the context of digital health applications (DiGA) in Germany, few studies have explored their effects specifically in insulin-treated people with diabetes." (PMID 40661654, 2025). "For example, wearable electrochemical aptamer sensors can monitor insulin concentrations in real time, enabling more rapid and accurate diabetes management." (PMID 40277546, 2025). "Intensive insulin therapy management in type 1 Diabetes Mellitus (T1D) is performedcontinuously and requires commitment, planning, and constant monitoring from boththe multidisciplinary team and the individuals with the disease." (PMID 41379990, 2025). "Integrated artificial pancreas devices with continuous glucose monitoring (CGM) and closed‐loop insulin delivery are crucial for diabetes management." (PMID 40955783, 2025). "Continuous Glucose Monitoring (CGM) systems are increasingly being utilized as alternative methods for monitoring blood glucose levels in patients with diabetes receiving insulin therapy." (PMID 40568192, 2025). "Diabetes is a multifaceted disorder characterized by deficits in carbohydrate metabolism that compromise insulin’s function in tissues and lead to elevated blood glucose levels." (PMID 40507585, 2025). "Resistance exercise exhibited superior efficacy in enhancing insulin sensitivity compared with alternative interventions in patients with diabetes (SUCRA score=71.8%)." (PMID 40951419, 2025). "It does not always require insulin for treatment and, therefore, is called an “insulin-independent” form of diabetes." (PMID 40144552, 2025). "In anti-diabetes treatment, rutin can reduce blood glucose, regulate insulin secretion, improve dyslipidemia, and activate IRS-2/PI3K/Akt/GSK-3β signaling pathways." (PMID 40864768, 2025). "TRO has been shown to inhibit hypothalamic PTP1B in obese rodents, thereby increasing the sensitivity of both the insulin and leptin receptors, correcting diabetes and obesity." (PMID 40123295, 2025). "Most patients used insulin throughout the COVID-19 period and experienced adjustments to their diabetes medication regimens." (PMID 40700264, 2025). "Management of diabetes in pregnancy is challenging due to limited treatment options, with insulin remaining the mainstay of therapy throughout pregnancy." (PMID 41227133, 2025). "Regular intake of curcumin has been found to improve glucose and lipid metabolism, enhance intracellular antioxidant responses, and improve insulin signaling, providing benefits for diabetes-related metabolic diseases." (PMID 39950117, 2025). "Currently, peroxisome proliferator-activated receptor (PPAR) agonists are widely deployed as frontline agents for glycemic regulation due to their substantial insulin-sensitizing properties, which effectively decelerate diabetes progression." (PMID 41216186, 2025). "Her glycemic control remains unstable, with significant variability on continuous glucose monitoring requiring frequent insulin titration, consistent with brittle diabetes." (PMID 41450393, 2025). "Glycemia monitoring is essential for patients suffering from diabetes, especially those under insulin treatment." (PMID 40648295, 2025).
diabetes (continued). "Hypoglycaemia is defined as blood glucose levels below the normal range and is a frequent adverse effect of diabetes treatment, especially with insulin or sulphonylureas." (PMID 41007688, 2025). "The ability of irradiated polysaccharides to elevate insulin levels and improve glucose uptake go in accordance to which highlights their potential as functional ingredients in managing diabetes." (PMID 40404997, 2025). "Users of insulin, SUs, and GLs had a higher rate of hypoglycemia than users of other diabetes drugs." (PMID 40777704, 2025). "DKA is not only linked to long-standing diabetes but also inducible by pancreatic tumors disrupting insulin production, leading to pancreatogenic diabetes mellitus." (PMID 40443601, 2025). "Tirzepatide should be considered as an effective treatment for metabolic Aimprovement of diabetes, insulin resistance and related complications." (PMID 40452043, 2025). "Diabetes specialists can expect models to consistently weigh recent glucose trends, insulin activity, meal history, and circadian timing as primary drivers." (PMID 41374669, 2025). "Growing evidence suggests that visceral fat tissue plays a more important role in insulin resistance and the development of diabetes than subcutaneous fat." (PMID 40235662, 2025). "This retrospective cross-sectional analysis assessed the regulatory role of microRNA-375 (miR-375) in the insulin signaling pathway and its clinical relevance for the treatment of type 2 diabetes mellitus (T2DM) in a Pakistani cohort." (PMID 40786421, 2025). "This section will define the physiological effects of insulin resistance in both uncomplicated pregnancies and those complicated by diabetes, as well as delineate the adverse outcomes of diabetic pregnancies for both mother and child." (PMID 40137145, 2025). "Daily life for patients with this rare disease is often challenging due to insulin-treated diabetes, visual and hearing impairments, the need for multiple medications, and frequent outpatient visits and examinations." (PMID 40988749, 2025). "Diabetes severity was approximated using fasting glucose, medication burden and insulin use; however, inclusion of HbA1c, hypoglycemia history, time in range or complication status would have enabled a more comprehensive evaluation." (PMID 41351230, 2025). "Diabetes, primarily type 2, involves impaired insulin production or utilization, leading to chronic hyperglycemia that damages blood vessels, nerves, and organs over time, increasing risks of heart disease, kidney failure, and blindness." (PMID 40565424, 2025). "Accordingly, we have recently demonstrated that sustained (P3)PP administration exerts positive effects on islet cell turnover, leading to augmented beta-cell mass and pancreatic insulin content in a rodent model of obesity-diabetes." (PMID 40362452, 2025). "One patient was diagnosed with new-onset diabetes as a result of undergoing steroid treatment; the other had worsening of preexisting diabetes and required insulin therapy." (PMID 39832019, 2025). "Type 2 diabetes mellitus is a multifactorial endocrine disorder characterized by chronic hyperglycemia, arising from insufficient insulin secretion, impaired insulin action, or a combination thereof." (PMID 40565591, 2025). "Diabetes is a chronic health condition resulting from insufficient insulin production by the pancreas or the body’s inability to utilize the insulin it generates effectively." (PMID 40057806, 2025). "Consistently, patients with insulin resistance (IR) or diabetes mellitus (DM) exhibited higher PGRMC1 expression in skeletal muscle compared to those with insulin sensitivity (IS)." (PMID 41208560, 2025). "Through further validation, we observed a decline in m6A modification levels in people with diabetes following intensive insulin therapy." (PMID 40299682, 2025).
diabetes (continued). "The most common symptoms of diabetes mellitus are high levels of blood glucose and decreased body weight due to insulin resistance or insufficient insulin synthesis." (PMID 41159201, 2025). "Stem cell treatments can revolutionize diabetes by restoring endogenous insulin production and achieving continuous glycemic control." (PMID 40405306, 2025). "Many of the current assays for protein and peptide biomarkers that are used in the diagnosis of diabetes and in clinical diabetes research, such as C-peptide, insulin, HbA1c, and AABs, are immunoassays, which solely rely on antibody reagents." (PMID 40056450, 2025). "The duration of diabetes was slightly longer in the insulin therapy group (10.5 ± 4.5 years) compared to the oral agents group (9.9 ± 4.1 years), but the difference was minimal." (PMID 40959330, 2025). "Inflammatory cytokines such as TNF-α, IL-1β, and IL-6 activate multiple signaling pathways, leading to insulin resistance, impaired insulin secretion, and promotion of diabetes and its complications." (PMID 41306290, 2025). "Consistent with the consensus agreement, persistent symptoms have been associated with metabolic and endocrine systems, potentially leading to diabetes through mechanisms involving pancreatic dysfunction and altered insulin responses." (PMID 40254579, 2025). "Diabetes mellitus (DM) is a chronic disease that occurs when the pancreas fails to produce insulin or when the body cannot effectively use the insulin it generates." (PMID 40644414, 2025). "Before propensity score matching, GLP-1 RAs users were generally younger and had longer diabetes duration, higher rates of diabetic complications, and more frequent use of thiazolidinedione and insulin." (PMID 40920377, 2025). "Mitochondria are central to the process that couples glucose metabolism to insulin exocytosis, and their dysfunction is an early feature of diabetes." (PMID 40765848, 2025). "To address this question, we employed a streptozotocin (STZ)-induced diabetes model in Wistar rats and compared standard insulin therapy with a combination of insulin plus sorafenib." (PMID 41169477, 2025). "Type 2 diabetes mellitus refers to a group of metabolic conditions characterized by prolonged hyperglycemia due to impaired production, secretion, or action of insulin." (PMID 40002867, 2025). "For the structured discussion, the panel was divided into subgroups according to the major themes of this article: (a) treatment options and glycemic targets, (b) insulin regimens, (c) diabetes with cardiovascular disease, and (d) diabetic kidney disease." (PMID 41299307, 2025). "Nonetheless, this researchrepresents a significant step toward the development of more effectiveand accessible insulin delivery systems for patients with Diabetes." (PMID 40488088, 2025). "Global efforts must be made to ensure universal accessibility to insulin and diabetes technologies and thereby improve disparity in glycemic outcomes for children with T1D." (PMID 40864470, 2025). "Long-term management of diabetes involves various responsibilities such as insulin use, dietary modifications and lifestyle changes." (PMID 40447901, 2025). "IRS1 and IRS2 in the insulin signaling pathway are dysregulated in diabetes mellitus, so they need to work in concert to maintain normal glucose metabolism and insulin sensitivity." (PMID 40747301, 2025). "Diabetes mellitus, often called diabetes, is a chronic condition characterized by the body’s inability to produce enough insulin or to use the insulin it produces effectively." (PMID 40006246, 2025). "Type 1 refers to the process of beta cell degeneration that can lead to diabetes, where insulin is required for survival to avoid ketoacidosis, coma, and death." (PMID 40552040, 2025). "An illustrative case is in diabetes management, where the precision modeling of glucose–insulin dynamics has informed personalized insulin therapy, improving blood sugar control and reducing complications." (PMID 39857751, 2025).